IGF1 (insulin like growth factor 1)
Diseases named in the same sentence as IGF1 in open-access papers (continued):
Sharing a sentence is not in itself a finding about the gene and the disease.
glioma (92 papers, 2010 to 2026). A benign or malignant brain and spinal cord tumor that arises from glial cells (astrocytes, oligodendrocytes, ependymal cells). "Exogenous IGF-1 can enhance the invasive and migratory capacity of glioma cells by binding to IGF-1R and has been associated with resistance of gliomas to radiation, chemotherapy, and immunotherapy." (PMID 40243478, 2025). "The IGF-1/IGF-1R axis was identified to underlie resistance to colony-stimulating factor-1 receptor (CSF-1R) inhibition in gliomas." (PMID 31805126, 2019). "A taller height has been linked with an increased risk of central nervous system tumors, and its effect on cancer risk may be partially mediated by IGF-1 levels." (PMID 40458457, 2025). "As lncRNAs ASLNC22381 and ASLNC20819 were upregulated, these might have important roles in the glioma pathway, and as they probably target IGF-1, they might therefore be associated with recurrence and malignant progression of glioma." (PMID 32650527, 2020). "In this study, CHOP RNAi blocking ER stress, 3-MA inhibiting autophagy and IGF-1 activating PI3K/AKT pathway could recover depression of cell viability caused by CERS1 overexpressed in glioma cells." (PMID 29262618, 2017). "Considering the role of IGF-1 in the proliferation, differentiation and apoptosis of glial cells, it is biologically plausible that physical inactivity, including in earlier life, may contribute to glioma risk." (PMID 35184245, 2022). "IGF1, on the other hand, was most expressed in myeloid and immune cells, validating our findings in mBT0309 that glioma cells express IGF2 to a greater degree." (PMID 41568176, 2026). "Among the available evidence, glioma-reactive astrocytes can secrete a variety of cytokines and chemokines, including IGF1, CCL20, TGF-β, IL-10, IL-12, IL1A/B, IL-2, CXCL10, and G-CSF." (PMID 40243478, 2025). "BDNF and glucose‐regulated protein 78 (GRP78) also contribute to this pro‐tumorigenic environment in gliomas, while IGF‐1 drives the growth of olfactory bulb glioma." (PMID 40685688, 2025). "Neuronal factors like neuroligin‐3 (NLGN3), brain‐derived neurotrophic factor (BDNF), and insulin‐like growth factor‐1 (IGF‐1) stimulate glioma proliferation." (PMID 40685688, 2025). "IGF-1 also reduced etoposide-induced apoptosis of glioma cells via Bcl-2 up regulation while inhibition of caspase-3 activity." (PMID 38956588, 2024). "In in vitro studies, transduction of IGF1 antisense RNA retroviruses inhibited glioma cells growth, while IGF1 AS-expressing episomal vectors have been used as anti-cancer vaccines." (PMID 38892104, 2024). "The IGF-1-induced upregulation of miR-513a-5p considerably reduced the expression of NEDD4L in glioma cells." (PMID 37568787, 2023). "This glioma cell line overexpresses several genes similar to those reported for human gliomas, such as the PDGFβ, insulin-like growth factor (IGF)-1, epidermal growth factor receptor (EGFR), and Erb3/Her3 precursor proteins." (PMID 37512530, 2023). "It is expressed in human brain (basal ganglia, hypothalamus, midbrain) and its expression in the context of glioma pathology it has been found to be mediated via insulin-like growth factor (IGF)-1 signaling networks." (PMID 36959545, 2023). "They showed that glioma development required neurosensory input from olfactory receptors and the release of neuronal IGF1, which then influenced tumor cells independently of synaptic formation." (PMID 36482431, 2022). "By stimulating the PI3K/AKT signaling pathway, insulin-like growth factor-1 (IGF-1) inhibits glioma cell death." (PMID 36497459, 2022). "Subsequently, they reported that BD IX rats, which had been immunized with the C6 anti-sense IGF-1 transfected cells, were resistant to both s.c. and i.c. challenge of the C6 glioma." (PMID 35446393, 2022). "IGF-1 at 200 ng/ml only increased the glioma cell growth ratio by 13% using MTT assays and 21% using cell counting assays compared to the control after 48 h of treatment." (PMID 31805126, 2019).
glioma (continued). "To explore the molecular functions of IGF-1 on glioma cell progression, we conducted a literature search." (PMID 31805126, 2019). "By increasing Bcl-2 expression and decreasing caspase-3 protease activity, IGF-1 significantly decreased the etoposide-induced apoptosis of glioma cells." (PMID 31805126, 2019). "A previous study suggested that blockade of the Hedgehog/GLI1-regulated IGF-1 pathways countered the intrinsic and acquired resistance of glioma stem cells to TMZ." (PMID 31805126, 2019). "NEDD4L, identified as a direct target gene of miR-513a-5p, was significantly downregulated in GBM patients and IGF-1-treated glioma cells." (PMID 31805126, 2019). "Then, these reduced phosphorylation levels of β-catenin led to increases in its endogenous level and downstream regulator expressions such as cyclin D1, suggesting that IGF-1 activated the WNT/β-catenin pathway in glioma U87-MG cells." (PMID 31805126, 2019). "By miRNA array analyses, 93 upregulated and 148 downregulated miRNAs were identified in IGF-1-treated glioma cells." (PMID 31805126, 2019). "In the present study, we attempted to identify IGF-1-influenced miRNA networks in reducing glioma cell sensitivity to TMZ treatment." (PMID 31805126, 2019). "IGF-1 also regulates inflammatory responses in glioma cells via influencing hypoxia-inducible factor (HIF)-1α-toll-like receptor 9 (TLR9) cross talk." (PMID 31805126, 2019). "Overexpression of NEDD4L inhibited glioma cell viability and reversed IGF-1-repressed TMZ cytotoxicity." (PMID 31805126, 2019). "Taken together, IGF-1-mediated miR-513a-5p upregulation significantly inhibited NEDD4L expressions in glioma cells." (PMID 31805126, 2019). "Repeated irradiation induces the self-renewal potential of glioma stem cells by increasing IGF1 secretion and upregulating IGF type 1 receptor expression." (PMID 29688867, 2018). "A subset of human gliomas appears to express IGF1 and/or IGF2, and evidence suggests that IGF2 contributes to the aggressive nature of some GBMs." (PMID 30231881, 2018). "Taken together, these results indicated that blocking IGF1 enhanced matrine‐induced senescence in glioma cells." (PMID 30079478, 2018). "In the present study, by an integrative network analysis, we identified relationships between the IGF-1/miR-181d axis and cytokine genes in glioma progression." (PMID 28389653, 2017). "Taken together, miR-181d plays a crucial vital role in mediating the crosstalk between IGF-1 signaling and cytokine expressions in glioma progression." (PMID 28389653, 2017). "Significant and dose-dependent decreases in miR-181d levels were observed in both IGF-1-treated glioma cell lines." (PMID 28389653, 2017). "An IGF-1-downregulated miRNA profile was obtained from miRNA array analyses with IGF-1-stimulated glioma U87-MG cells and TCGA database." (PMID 28389653, 2017). "The miR-720, miR-181b21, miR-13922, and miR-323-5p23 have been reported to target to the IGF-1 receptor, resulting in influencing the effects of IGF-1 signaling on glioma development." (PMID 28389653, 2017). "The miR-181d, that targeted the most IGF-1-related cytokine genes, was significantly reduced in IGF-1-treated glioma cells." (PMID 28389653, 2017). "To reconfirm the array data, we measured changes in miR-181d expression levels in IGF-1-treated glioma U87-MG and M059K cells." (PMID 28389653, 2017). "Several studies reported the relationships between IGF-1 signaling and miRNA regulation involved in mediating physiological processes and disease development, especially in glioma." (PMID 28389653, 2017). "Experiments done with murine glioma stem cells, exposed to fractionated radiation, showed upregulation of IGF-1 receptor and increased IGF-1 secretion, leading to enhanced self-renewal of glioma stem cell populations along with Akt activation." (PMID 27043632, 2016).
glioma (continued). "It plays a key role in AKT pathway activation during glioma development and progression and its knockdown has been shown to decrease IGF1-stimulated AKT activation in vascular smooth muscle cells and acute leukemia cells." (PMID 26317790, 2015). "Furthermore, the insulin-like growth factor 1 (IGF-1) has been shown to trigger TLR9 expression in glioma cells through activation of hypoxia-induced factor 1 alpha signaling, which in turn stimulates IL-1β, IL-6, IL 8 as well as CXCR4." (PMID 41157253, 2025). "Targeted ablation of IGF1 in M/T cells has been demonstrated to effectively curtail the proliferation of mutated oligodendrocytes and to impede tumor progression, emphasizing the critical role of IGF‐1 in glioma development." (PMID 39469896, 2024). "Glioma may acquire resistance driven by elevating levels of high IGF-1R and macrophage-derived IGF-1, which enhance survival and invasion of glioma cells." (PMID 37012233, 2023). "However, after prolonged treatment with CSF1R inhibitors, IL4 accumulated from other TME cell types stimulated TAMs to secrete insulin-like growth factor 1 (IGF1), which in turn sustains the survival and growth of glioma cells." (PMID 37190507, 2023). "Additionally, the expression levels of HRAS, MAPK1, IGF1, and IGF1R in glioma cells have been closely linked to the growth, invasion, and metastasis of glioma." (PMID 37865727, 2023). "Besides the benefits of microglia phagocytosis, the pro‐function of glioma cells of IGF‐1 should also be considered." (PMID 37849438, 2023). "IGF-1 has been strongly suggested to be involved in the pathogenesis of gliomas." (PMID 36088507, 2022). "Physical activity might influence the process of carcinogenesis through lowering free insulin and IGF-1 levels; however, it seems that the binding of these molecules to their proteins is very low in glioma." (PMID 35045870, 2022). "However, gliomas developed resistance to CSF-1R through the PI3K mediated release of insulin-like growth factor 1 (IGF-1)." (PMID 33919732, 2021). "In glioma, IGF‐1 could modulate miR‐513a‐5p expression to affect the NEDD4L/Wnt/β‐catenin signalling pathway and desensitize glioma cells to temozolomide." (PMID 32342645, 2020). "The mechanisms of IGF-1-influenced TMZ resistance in glioma cells are still unclear." (PMID 31805126, 2019). "In gliomas, IGF-1 modulates cell proliferation and strongly stimulates cell migration." (PMID 31805126, 2019). "Furthermore, knockdown of endogenous β-catenin levels significantly attenuated IGF-1-induced cyclin D1 and cell growth, suggesting that IGF-1 induced β-catenin signaling activation in glioma cells." (PMID 31805126, 2019). "Furthermore, increasing evidence suggests that IGF-1 signaling is involved in drug resistance mechanisms, resulting in glioma progression." (PMID 31805126, 2019). "To explore whether miRNAs participate in IGF-1-mediated glioma cell sensitivity to TMZ treatment, we conducted an miRNA microarray analysis using cells treated with 200 ng/ml IGF-1 for 48 h." (PMID 31805126, 2019). "Finally, our results suggest that IGF-1-upregulated miR-513a-5p signaling attenuated glioma cell sensitivity to TMZ via inhibiting NEDD4L-inactivated WNT/β-catenin pathways." (PMID 31805126, 2019). "IGF-1 treatment significantly reduced endogenous NEDD4L levels in glioma cells." (PMID 31805126, 2019). "Finally, reduced endogenous miR-181d and increased IL-1b/CCR1 levels were identified in IGF-1-stimulated glioma cells." (PMID 28389653, 2017). "Target gene-related pathway analysis indicated that ASLNC22381 and ASLNC20819 may play important roles via their target insulin-like growth factor 1 (IGF-1) genes, which has been thought to be a positive risk factor for human glioma development." (PMID 28293170, 2017).
glioma (continued). "As a consequence, we concluded that IGF-1-enhanced cytokine expressions targeted by miR-181d in glioblastoma could be beneficial to understanding glioma development and to provide novel therapeutic targets of future glioma therapies." (PMID 28389653, 2017). "Finally, we tried to investigate the effects of IGF1-miR181d-cytokines axis on glioma cell growth and invasion." (PMID 28389653, 2017). "Within the framework of cancer neuroscience, research has illuminated that the secretion of BDNF and IGF‐1, coupled with direct synaptic interactions between glutamatergic and GABAergic neurons and OPCs, plays a crucial role in the malignant transformation of OPCs into glioma cells." (PMID 39469896, 2024). "These all indicated that IGF‐1 could benefit glioma phagocytosis by microglia." (PMID 37849438, 2023). "Furthermore, the microglia could be the target cell with elevated IGF‐1/IGF‐1R signaling in the glioma treatment." (PMID 37849438, 2023). "In glioma, a specific mutation in phosphatase and tensin homologue (PTEN) gene, a tumor suppressor and lipid phosphatase, determines the truncation of its C-terminal region with consequent gain of neo-morphic and phosphatase-independent activity, which stimulates IGF1 synthesis." (PMID 33673232, 2021). "In our previous study, we also found that miR-128 could target to IGF-1-mediated mammalian target of rapamycin (mTOR) signaling in temozolomide-induced glioma cell apoptotic death, suggesting that microRNAs play critical roles in regulating IGF-1 signaling involved in glioma progression." (PMID 28389653, 2017). "CSF-R1 inhibition enhances IGF-1 and PI3K signaling in murine glioma, creating treatment resistance." (PMID 40422244, 2025). "Glioma cells can become more vulnerable to TMZ-induced cell death by decreasing pro-survival pathways, which is achieved by lowering insulin/IGF-1 signaling." (PMID 38891882, 2024). "This intricate interplay between neurons and glioma cells, mediated by paracrine signals such as BDNF, NLGN3, and IGF‐1, underscores the complexity of the TME in brain tumors and highlights potential therapeutic targets for future interventions." (PMID 39469896, 2024). "The binding of the IGF-1 with IGF-1R results in its activation by autophosphorylation that promotes cell migration and proliferation in gliomas." (PMID 38956588, 2024). "Moreover, in glioma cells, insulin-like growth factor 1 (IGF-1) could induce TLR9 expression through hypoxia-induced factor 1 alpha signaling, which further leads to secretion of cytokines IL-1β, IL-6, IL-8, and CXCR4 (a chemokine receptor that plays an important role in cell migration)." (PMID 34715891, 2021). "Co-culture of BMSCs and glioma cells was found to inhibit angiogenesis in gliomas by down-regulating the expression of angiogenic markers such as PDGF-BB, IGF-1, FGF-2, and IL-1b." (PMID 31864321, 2019). "Knockdown of endogenous β-catenin levels also reduced IGF-1-insensitized TMZ cytotoxicity and DNA damage, suggesting that IGF-1 reduces glioma cell sensitivity to TMZ treatment via activating the WNT/β-catenin pathway." (PMID 31805126, 2019). "To test the effects of IGF-1 on endogenous levels of IL-1b and CCR1 in glioma cells, we measured mRNA and protein levels of IL-1b and CCR1 in IGF-1-stimulated glioma cells by real-time qPCR assays and immunoblotting analyses." (PMID 28389653, 2017). "In vivo, starvation for 48 hours, which causes a significant reduction in blood glucose and circulating insulin-like growth factor 1 (IGF-1) levels, sensitized both subcutaneous and intracranial glioma models to radio-and chemotherapy." (PMID 22984531, 2012). "These include epidermal growth factor (EGF), platelet-derived growth factor (PDGF), insulin-like growth factor 1 (IGF-1), and their specific receptors (EGFR, PDGFR, and IGFR), all of which are involved in autocrine or paracrine signaling in gliomas." (PMID 22091432, 2011).
glioma (continued). "The IGF-1/IGF-1R signaling can activate the PI3K/AKT/mTOR pathway signaling pathway, which is closely related to AKT1 and PIK3CD and plays a critical role in glioma progression, promoting cancer cell proliferation and inducing drug resistance." (PMID 38665430, 2024). "It is known that IGF1 has direct effects on stimulating glycolytic flux favoring tumor cell energy production, acting through IGF1R to increase the GLUT1 expression, the main glucose transporter in glial tumors." (PMID 35574033, 2022). "While most human glioma cell lines do not express IGFs, a subgroup of human gliomas were reported to express IGF1 and/or IGF2, indicating a possible autocrine component." (PMID 30231881, 2018). "Consequently, IGF-1-enhanced cytokine IL-1b and CCR1 signaling via inhibiting miR-181d is involved in glioma progression." (PMID 28389653, 2017). "Given that BA has previously been implicated in blocking diverse canonical YY1/FAS, ERβ, insulin/IGF‐1, MAPK/ERK and Notch signalling pathways in different pathological models, we next investigated which pathway was responsible for UBE2T downregulation in glioma." (PMID 41486508, 2026). "As the glioma cells were not proliferated in vivo and in vitro co‐culture systems, the concentration of IGF‐1 secreted by microglia might be low enough and affect microglia itself locally." (PMID 37849438, 2023). "IGF-1 was a growth factor in a variety of malignant cells, and existing studies have confirmed that high circulating levels of IGF-1 increase cancer risk, and gliomas are no exception." (PMID 37891770, 2023). "Furthermore, no studies have reported if IGF-1-regulated miRNAs participate in drug resistance or glioma progression." (PMID 31805126, 2019). "IGF-1 treatment attenuated TMZ cytotoxicity via WNT/β-catenin signaling, but did not influence glioma cell growth." (PMID 31805126, 2019).